CCL18 (C-C motif chemokine ligand 18)
Diseases named in the same sentence as CCL18 in open-access papers (continued):
Sharing a sentence is not in itself a finding about the gene and the disease.
atherosclerosis (5 papers, 2014 to 2024). A disease characterized by the build-up of fatty material and calcium deposition in the arterial wall resulting in partial or complete occlusion of the arterial lumen. "Our work thus provides evidence and a molecular foundation for its causal involvement in atherosclerosis and paves the way for CCL18-targeted treatment measures." (PMID 38807599, 2024). "On the basis of its expression in atherosclerotic plaque and the reported T-cell chemotactic activity, we postulated that CCL18 is causally implicated in the pathophysiology of atherosclerosis." (PMID 38807599, 2024). "Next, we studied the ability of CCL18 to drive CCR6-mediated responses in vivo in two models of inflammation: CCL18-dependent ear swelling and the more complex mouse model of atherosclerosis." (PMID 38807599, 2024). "Recent observations of elevated CCL18 plasma levels in patients with acute cardiovascular syndromes prompted an investigation into the role of CCL18 in the pathogenesis of human and mouse atherosclerosis." (PMID 38807599, 2024). "Collectively, our findings implicate the CCL18/CCR6 axis in the pathogenesis of atherosclerosis." (PMID 38807599, 2024). "Regarding atherosclerosis, CCL18 treatment deteriorated plaque formation in WTD-fed ApoE−/− mice." (PMID 38807599, 2024). "Moreover, macrophage expression of CCL18 in patients with atherosclerosis was significantly higher as compared with controls, suggesting CCL18 has a role in atherosclerotic plaque formation." (PMID 27573044, 2016). "Our studies are the first to identify the CCL18/CCR6 axis as a regulator of immune responses in advanced murine and human atherosclerosis." (PMID 38807599, 2024). "Moreover, the bulk of CCR6 staining colocalized with CD3+ T cells, and a tight correlation was observed between plaque CCL18 and CCR6 expression at mRNA level, lending further support to a link between CCR6 and CCL18 in atherosclerosis." (PMID 38807599, 2024). "Fourth, CCL18 administration in hyperlipidemic CCR6−/− mice neither did aggravate atherosclerosis nor did induce T-cell accumulation in plaque, unlike WT mice that rendered hyperlipidemic by PCSK9 gene transfer." (PMID 38807599, 2024). "CCL18/CCR6 may therefore be a candidate for intervention in atherosclerosis-related inflammation, albeit that our limited understanding of chemokine pathways relevant to human atherosclerosis, in mutual interaction, warrants further study." (PMID 38807599, 2024).
hypersensitivity pneumonitis (5 papers, 2020 to 2025). Hypersensitivity pneumonitis (HP) is a pulmonary disease with symptoms of dyspnea and cough resulting from the inhalation of an antigen to which the subject has been previously sensitized. "Just three years after this discovery, it was found that CCL18 mRNA is up-regulated in the lungs of patients with hypersensitivity pneumonitis." (PMID 38334630, 2024). "However, its diagnostic utility in identifying IPF is limited, as Cai M and co-authors revealed that CCL18 serum levels are also significantly elevated in other ILDs, such as hypersensitivity pneumonitis." (PMID 37893169, 2023). "Indeed, expressed CCL18 levels were significantly increased in BAL-derived cells from IPF patients compared to patients with other fibrotic diseases, such as sarcoidosis or hypersensitivity pneumonitis, and healthy controls." (PMID 37893169, 2023).
Obesity (5 papers, 2020 to 2025). Accumulation of substantial excess body fat. "Two hub genes (CCL18 and C1QC) associated with both obesity and DN were ultimately identified by constructing a PPI network." (PMID 39526504, 2024). "Taken together, our findings indicate that C1QC and CCL18, as intermediaries between DN and obesity, may play major roles in the development of type 2 DN and obesity and may constitute the pathological mechanism by which obesity contributes to DN." (PMID 39526504, 2024). "Two hub genes (CCL18 and C1QC) were ultimately identified by constructing a PPI network; these genes may both be involved in the development of type 2 DN and obesity." (PMID 39526504, 2024). "Morbid obesity, regardless of the degree of insulin resistance, was associated with changes in the expression of genes involved in pro- (such as CD86 and S100A8) and anti-inflammatory (such as CCL18 and ZBTB16) responses." (PMID 35625760, 2022).
oral squamous cell carcinoma (5 papers, 2020 to 2025). "For example, CCL18 has been shown to promote the proliferation of oral squamous cell carcinoma cells and recruit naive CD4+ T cells into the tumor microenvironment, leading to their differentiation into regulatory T cells that contribute to tumor immune evasion." (PMID 40433389, 2025). "Moreover, for oral squamous cell carcinoma, CCL18 level is an independent prognostic factor of overall and disease-free survival time." (PMID 35609322, 2022). "In addition, the promotion effect of CCL18 on oral squamous cell carcinoma cell proliferation and metastasis by inducing linc00319 expression to regulate miR-199a-5p/frizzled class receptor 4 axis." (PMID 35609322, 2022). "CCL18/PITPNM3 axis also activates JAK2/STAT3 signaling pathway to promote the growth and metastasis of oral squamous cell carcinoma cells." (PMID 35609322, 2022).
acute lymphoblastic leukaemia (4 papers, 2009 to 2024). "CCL18/PARC has been found to be overexpressed in the serum of acute lymphoblastic leukaemia patients and in the ascitic fluid of patients with ovarian carcinoma." (PMID 19832977, 2009). "In addition, the receptor GPR30 was reported to mediate CCL18 inhibition of CXCL12-stimulated chemotaxis on pre-B acute lymphocytic leukemia cells." (PMID 39259753, 2024).
atopic dermatitis (4 papers, 2021 to 2022). "The chemokine CCL18 is produced in cells of the myelomonocytic lineage and represents one of the most highly expressed chemokines in lesional skin and serum of atopic dermatitis patients." (PMID 34769080, 2021). "The histamine-induced CCL18 upregulation in IL-10-activated M2 macrophages was almost similar in cells obtained from atopic dermatitis patients compared to cells from healthy control persons." (PMID 34769080, 2021). "Importantly, among a variety of chemokines, CCL18 represents the most abundant one in the skin of atopic dermatitis (AD) patients." (PMID 34769080, 2021). "One argument in favor of this hypothesis is given by the analysis of skin lesions of atopic dermatitis patients where NK cells were detected in the epidermis in close contact with CD1a+ dendritic cells, while all CCL18-expressing cells in the epidermis were CD1a+." (PMID 33918621, 2021).
coronary artery disease (4 papers, 2011 to 2024). "More recently, CCL18 has been proposed as a potential diagnostic and prognostic parameter in patients with stable coronary artery disease." (PMID 21447198, 2011). "CCL3, CCL18, CXCL12/SDF-1, CXCL16, IGF1 and IL10 have been linked to pro-angiogenesis and/or coronary artery diseases." (PMID 23496821, 2013). "In patients with stable chest pain, CCL18 correlated with the extent of coronary artery disease (CAD), but did not provide independent prognostic information." (PMID 38596196, 2024).
cutaneous T-cell lymphoma (4 papers, 2016 to 2023). "High expression of serological CCL18 is associated with significantly poor prognosis in patients of cutaneous T-cell lymphomas." (PMID 37500057, 2023). "Additionally, the presence of macrophages with an M2 phenotype was described as cutaneous T-cell lymphoma, which produces the chemokines CCL18 and CXCL10." (PMID 36765704, 2023). "The chemokines CCL8 and CCL18, which are known to bind CCR8, were found to be highly expressed in the skin of cutaneous T-cell lymphoma patients and may play a role in the homing of CCR8-expressing lymphocytes to the skin in these patients." (PMID 36765704, 2023).
diabetes (4 papers, 2012 to 2021). "In patients with newly diagnosed T2DM, activation of the anti-inflammatory response was maintained; however, there was a significant (p < 0.001) decrease in the stimulated secretion of CCL18 in patients with a diabetes duration of more than 10 years." (PMID 31877847, 2019). "The basal secretion of CCL18 by monocytes from patients with long-term diabetes without DFS was significantly lower (3.0 (0; 9.6) pg/mL) compared to patients with DFS (9.4 (3.1; 40.1) pg/mL)." (PMID 31877847, 2019).
head and neck squamous cell carcinoma (4 papers, 2021 to 2025). A squamous cell carcinoma that arises from any of the following anatomic sites: lip and oral cavity, nasal cavity, paranasal sinuses, pharynx, larynx, and salivary glands. "In head and neck squamous cell carcinoma (HNSCC), SPP1+CCL18+ and SPP1+FOLR2+ tumor-associated macrophages (TAMs) harbored pro-angiogenic and metastatic transcriptional programs and were correlated with poor survival." (PMID 39409192, 2024).
liver cancer (4 papers, 2022 to 2023). An epithelial or non-epithelial malignant neoplasm that arises from the liver. "Additionally, previous study showed that CCL18/PITPNM3 activated NF-kB signaling to enhance migration, invasion, and EMT of liver cancer cells." (PMID 35609322, 2022).
lymphoma (4 papers, 2022 to 2025). A malignant (clonal) proliferation of B- lymphocytes or T- lymphocytes which involves the lymph nodes, bone marrow and/or extranodal sites. "CCL18 is known to be secreted by M2-polarized tumor-associated macrophages and is associated with immunosuppression and tumor progression in various cancers, including lymphomas." (PMID 41472741, 2025). "Although CCR3, CCR6, CCR8, PITPNM3, and GPER1 encode receptors of CCL18, only CCR6 was expressed in the lymphoma cells." (PMID 39894788, 2025). "Our observation that C-C motif chemokine ligand 18 (CCL18), which has a well-recognized role in lymphoma, was upregulated in our BCNHL analysis is relevant since this gene assists large B-cell lymphoma in cell proliferation, the NF-Kappa-B pathway, and the PI3K-AKT pathway." (PMID 36873459, 2022). "Other studies have also reported that cytokines (including CCL3, CCL4, and CCL18) may affect the lymphoma microenvironment and patient survival both in DLBCL and MCL." (PMID 35452413, 2022). "Given the well-established role of M2 macrophages in promoting an immunosuppressive tumor microenvironment, this finding suggests that CCL18 may contribute to lymphoma progression by fostering pro-tumorigenic signaling and impaired antitumor immunity in ABC lymphomas." (PMID 41472741, 2025). "RNA sequencing revealed upregulated expression of chemokine genes, including CCL5, CCL18, and CCL19, in WDL and that of the corresponding chemokine receptor genes CCR4, CCR6, and CCR7 in the lymphoma cells." (PMID 39894788, 2025). "Upregulated expression of CCR4 for CCL5, CCR6 for CCL18, and CCR7 for CCL19 was observed in lymph nodes, where lymphocytes were replaced by lymphoma cells." (PMID 39894788, 2025). "The expression of CCL5, CCL18, and CCL19 was further upregulated in WDL with prominent lymphoma cell infiltration compared with that with scant lymphoma cell infiltration." (PMID 39894788, 2025). "Although CCL18 expression was negligible in the lymph node, it was further upregulated in WDL with prominent lymphoma cell infiltration." (PMID 39894788, 2025). "The expression of chemokine receptors, CCR4 for CCL5, CCR6 for CCL18, and CCR7 for CCL19, was upregulated in lymph nodes with conspicuous lymphoma infiltration, likely representing their expression in lymphoma cells." (PMID 39894788, 2025). "Among them, over-expressed CCL18, CCL19, CXCL9, CXCL10, and CXCL13 were listed in the top 20 deregulated genes in all lymphoma datasets." (PMID 35452413, 2022).
Peritoneal Fibrosis (4 papers, 2013 to 2023). Disorder characterized by a wide range of structural changes in PERITONEUM, resulting from fibrogenic or inflammatory processes. "Given that CCL18 is involved in fibrotic processes and that recurrent peritonitis is a major risk factor for developing peritoneal membrane failure and peritoneal fibrosis, we sought to evaluate CCL18 protein concentrations in peritoneal effluents from patients experiencing peritonitis episodes." (PMID 29850544, 2018). "Given recurrent peritonitis is a risk factor for peritoneal fibrosis and UFF, the concentration of CCL18 was evaluated in a group of 39 PD patients with infectious peritonitis." (PMID 29850544, 2018). "Considering the role played by inflammation in peritoneal fibrosis during PD, we studied the effects of paricalcitol in the production of CCL18." (PMID 29850544, 2018). "Previous studies propose CCL18 as a marker and mediator of peritoneal fibrosis and UFF in patients treated with PD." (PMID 29850544, 2018). "The production of CCL18 by eosinophils in EP provides a new additional explanation for the association of recurrent EP during PD with UFF and potentially peritoneal fibrosis." (PMID 29850544, 2018). "In patients with CKD undergoing peritoneal dialysis treatment, CCL18 levels in peritoneal effluent correlated with progressive ultrafiltration failure and peritoneal fibrosis, suggesting that CCL18 could also be a biomarker of peritoneal damage." (PMID 34307414, 2021). "In PD patients, several chemokines, such as CCL18, released by activated macrophages owing to peritonitis episodes or long-term PD have been correlated with decreased peritoneal function and may contribute to peritoneal fibrosis." (PMID 38136175, 2023). "In terms of peritoneal fibrosis, CCL18 has been demonstrated to herald the development of peritoneal functional deterioration in PD patients, in whom the ability of peritoneal macrophages to stimulate fibroblast proliferation is correlated with CCL18 mRNA levels." (PMID 29850544, 2018).
acute coronary syndrome (3 papers, 2012 to 2024). Signs and symptoms related to acute ischemia of the myocardium secondary to coronary artery disease. "Notably, chemokines CCL3, CCL5 and CCL18 were identified as the risk factors of short-term mortality in patients with acute coronary syndromes." (PMID 36231033, 2022). "Hazard Ratios (95% confidence intervals) for a fatal future cardiovascular event during follow-up in patients with the acute coronary syndrome, according to baseline levels of CCL3/MIP-1α, CCL5/RANTES and CCL18/PARC, Bad Nauheim ACS II registry." (PMID 23029252, 2012).
cervical cancer (3 papers, 2012 to 2022). A primary or metastatic malignant neoplasm involving the cervix. "As a biomarker of malignant disease, CCL18 has been reported to be indicative of ovarian and cervical cancer." (PMID 22629457, 2012). "A study analyzing differential gene expression in 33 solid tissue samples identified CCL18 as one of twenty transcripts significantly over-expressed in invasive cervical cancers." (PMID 22629457, 2012).
cutaneous melanoma (3 papers, 2020 to 2022). A primary melanoma arising from atypical melanocytes in the skin. "The highest up-regulation was found for the CCL18 gene, highly expressed also in cutaneous melanoma, breast, ovarian, and other cancers." (PMID 33348918, 2020).
endometrial cancer (3 papers, 2020 to 2023). Primary or metastatic malignant neoplasm involving the endometrium (mucous membrane that lines the endometrial cavity). "The studies included have demonstrated a downregulation of epithelial marker E-cadherin in endometrial cancer cells by TGF-β treatment, AMF treatment, and IL-6 treatment and when treated with chemokine CCL18 and RANK/RANKL/CCL20." (PMID 36766756, 2023). "N-cadherin was over expressed when endometrial cancer cells were treated with TGF-β, IL-6, chemokines CCL18, RANK/RANKL/CCL20, and CXCR4/CXCL12." (PMID 36766756, 2023). "CCL18 seems to activate mTOR via the PI3K→Akt/PKB pathway, as shown by experiments on endometrial cancer cells." (PMID 33114763, 2020).
eosinophilia (3 papers, 2016 to 2022). "The role of DLCO in the evaluation of SSc-ILD patients may be highlighted: the decrease in DLCO correlates not only with the presence of neutrophilia or eosinophilia on BAL, but also with the BAL CD19 percentage count, inverted CD4/CD8 ratio, and CCL-18 concentrations." (PMID 36559035, 2022).
fibrosis (3 papers, 2023 to 2025). the formation of excess fibrous connective tissue in an organ or tissue in a reparative or reactive process. "CCL18-stimulated fibroblasts from fibrosis patients released significantly more FGF2 compared with CCL18-stimulated control fibroblasts." (PMID 38334630, 2024). "Most interestingly, a mouse model of bleomycin-induced fibrosis showed that the administration of human CCL18 via an adenoviral vector increased TNF-, IFNγ-, MMP-2 and MMP-9 expression and increased lymphocytosis but attenuated unexpectedly the bleomycin-induced collagen deposition." (PMID 38334630, 2024).
gastritis (3 papers, 2010 to 2020). Inflammation of the stomach. "H. pylori-infected individuals with uncomplicated gastritis showed a significantly elevated expression of mRNA for both M1 (iNOS, 8-fold; CXCL11, 20-fold) and M2 markers (CCL17, 30-fold; CCL18, 70-fold, CD206, 2-fold) compared to uninfected volunteers." (PMID 21124899, 2010).
Granuloma (3 papers, 2015 to 2023). A compact, organized collection of mature mononuclear phagocytes, which may be but is not necessarily accompanied by accessory features such as necrosis. "Their data revealed that the M2 polarization of CCL18-positive macrophages with TYROBP and TGF-β expression was crucial for granuloma formation." (PMID 38067175, 2023). "The expression levels of CXCL10, CXCL11, CCR7, CCL17 and CCL18 in the tuberculous granuloma were measured by quantitative real-time RT-PCR and were compared with the levels detected in lung tissues without granulomas." (PMID 26091535, 2015).
invasive breast carcinoma (3 papers, 2015 to 2025). A carcinoma that infiltrates the breast parenchyma. "Studies done on invasive breast carcinoma patient samples have shown that breast TAMs produce CCL18 which can increase the adherence of cancer cells to the ECM and promote migration." (PMID 33374595, 2020). "Studies done on invasive breast carcinoma patient tissue samples have shown that high expression of CCL18 in TAMs correlates with metastasis." (PMID 33374595, 2020). "Our previous study demonstrated that CCL18-positive TAMs are abundant in invasive breast cancer but are absent in benign breast tissue." (PMID 26244871, 2015).
lysosomal storage disorder (3 papers, 2011 to 2024). "It should be borne in mind that elevations in CCL18/PARC concentration are not exclusively caused by lysosomal disorders." (PMID 28222799, 2017). "We evaluated two different diagnostic pathways incorporating two well characterized biomarkers that have previously been used to monitor lysosomal storage disease progression (ChT activity and CCL18/PARC concentration) alongside appraisals of clinical symptoms and NP-C SI assessments." (PMID 28222799, 2017).
osteoarthritis (3 papers, 2013 to 2021). A noninflammatory degenerative joint disease occurring chiefly in older persons, characterized by degeneration of the articular cartilage, hypertrophy of bone at the margins and changes in the synovial membrane. "In the synovial fluid samples of Osteoarthritis (OA) patients CCL18 levels of 307 ± 92.5 ng/ml (n = 6) were detected." (PMID 23874339, 2013). "We performed immunohistochemical staining to explore the expression patterns of chemokines (CCL13, CCL18, and CCL3) in the synovial membrane of RA subgroups, while the osteoarthritis (OA) synovial membrane was used as controls." (PMID 34404786, 2021).